ELL3 (elongation factor for RNA polymerase II 3)
Description:
Enhancer-binding elongation factor that specifically binds enhancers in embryonic stem cells (ES cells), marks them, and is required for their future activation during stem cell specification. Does not only bind to enhancer regions of active genes, but also marks the enhancers that are in a poised or inactive state in ES cells and is required for establishing proper RNA polymerase II occupancy at developmentally regulated genes in a cohesin-dependent manner. Probably required for priming developmentally regulated genes for later recruitment of the super elongation complex (SEC), for transcriptional activation during differentiation. Required for recruitment of P-TEFb within SEC during differentiation. Probably preloaded on germ cell chromatin, suggesting that it may prime gene activation by marking enhancers as early as in the germ cells. Promoting epithelial-mesenchymal transition (EMT) (By similarity). Elongation factor component of the super elongation complex (SEC), a complex required to increase the catalytic rate of RNA polymerase II transcription by suppressing transient pausing by the polymerase at multiple sites along the DNA. Component of the little elongation complex (LEC), a complex required to regulate small nuclear RNA (snRNA) gene transcription by RNA polymerase II and III.
Synonyms: FLJ22637
Tractability: PROTAC: ubiquitination databases record sites on it.
Gene: Protein-coding gene on chromosome 15 (43,772,605 to 43,777,315, reverse strand). Ensembl gene ENSG00000128886.
Subcellular location: Nucleus
Subcellular location (Human Protein Atlas): Nucleoli; Nucleoplasm; Mitotic chromosome
Pathways (Reactome):
Gene expression (Transcription): RNA polymerase II transcribes snRNA genes
Gene Ontology:
Molecular function: protein binding; cis-regulatory region sequence-specific DNA binding
Biological process: DNA-templated transcription elongation; positive regulation of DNA-templated transcription, elongation; positive regulation of transcription by RNA polymerase II; snRNA transcription by RNA polymerase II; transcription elongation by RNA polymerase II; positive regulation of snRNA transcription by RNA polymerase II; positive regulation of transcription elongation by RNA polymerase II; regulation of epithelial to mesenchymal transition; spermatogenesis; stem cell differentiation; transcription by RNA polymerase II
Cellular component: nucleoplasm; nucleus; transcription elongation factor complex
Genetic constraint (gnomAD): Loss-of-function variants: 48 observed, 59.98 expected, observed/expected ratio (o/e) 0.8, 90% interval 0.63 to 1.02. The upper end of that interval is the gene's LOEUF score, 1.02, which puts it in group 4 of 6, group 1 being the genes least tolerant of losing a copy. Missense variants: 458 observed, 493.68 expected, observed/expected ratio (o/e) 0.93, 90% interval 0.86 to 1. Synonymous variants: 174 observed, 178.68 expected, observed/expected ratio (o/e) 0.97, 90% interval 0.86 to 1.1.
Homologues: Orthologues: chimpanzee ELL3 (99% identical), macaque ELL3 (94% identical), dog ELL3 (81% identical), mouse Ell3 (76% identical), rat Ell3 (76% identical), rabbit ELL3 (76% identical), pig ELL3 (70% identical), guinea pig ELL3 (66% identical), zebrafish si:ch211-13k12.2 (31% identical), Drosophila melanogaster Su(Tpl) (23% identical), Caenorhabditis elegans ell-1 (14% identical), zebrafish marveld2l (14% identical), and 1 more. Paralogues in human: ELL2 (31% identical), ELL (31% identical), MARVELD2 (17% identical), OCLN (14% identical), OCEL1 (11% identical).
Diseases named in the same sentence as ELL3 in open-access papers:
ELL3 is named in the same sentence as 11 diseases in open-access papers, as found by Europe PMC text mining. Sharing a sentence is not in itself a finding about the gene and the disease. The quoted sentences say what the papers report.
breast carcinoma (5 papers, 2015 to 2021). "For example, Ell3 is involved in the differentiation efficiency of embryonic stem cells, whereas Ell3 regulates anticancer drug responses in breast cancer cells." (PMID 30654843, 2019). "In this study, we demonstrated that ER(α), GATA3 and FOXA1 form a transcriptional complex with Ell3 to regulate IL-20 expression in ER(+) breast cancer cells." (PMID 28514748, 2017). "IL-20 expression is regulated by a transcription elongation factor, Ell3, in estrogen receptor-positive (ER(+)) breast cancer cells." (PMID 28514748, 2017). "To extend our understanding of the function of Ell3 in breast cancer, we used public microarray datasets to analyze the expression level of the Ell3 gene in 209 resected breast tumors (GSE2034) and in 52 human breast cancer cell lines (GSE41313)." (PMID 26540344, 2015). "In a previous study, we reported that Ell3 in breast cancer cell lines induces resistance to 5-fluorouracil via a MEK/ERK-dependent signaling pathway." (PMID 26540344, 2015). "To elucidate the meaning of Ell3 expression in breast cancer cells, we engineered MCF7 cells to overexpress Ell3 and examined the response of these cells to CDDP." (PMID 26540344, 2015). "Because Ell3 is an additional factor to the triple complex of ER(α), GATA3 and FOXA1 and this complex fine-tunes the expression level of IL-20, it will be essential to assess the clinical meaning of the expression of FOXA1 in combination with the expression of Ell3 in ER(α) breast cancer patients." (PMID 28514748, 2017). "In this study, we showed that expression of the pro-inflammatory cytokine IL-20 was regulated by a transcriptional complex composed of the transcription factors ER(α), GATA3, and FOXA1 and the transcriptional elongation factor Ell3 in ER(+) breast cancer cells." (PMID 28514748, 2017). "In this study, we show that Ell3, ER(α), GATA3 and FOXA1 form a transcriptional complex to regulate IL-20 expression in ER(+) breast cancer cell lines." (PMID 28514748, 2017). "In a previous study, we reported that transcription elongation factor Ell3 directly regulates IL-20 expression in an ER(+) breast cancer cell line, MCF7, but not in ER(−) breast cancer cell lines." (PMID 28514748, 2017). "In summary, our findings have shown that IL-20 expression in breast cancer is regulated by a transcriptional complex composed of transcription factors, including ER(α), GATA3, and FOXA1, as well as a transcriptional elongation factor, Ell3." (PMID 28514748, 2017).
breast tumors (1 paper, 2015). "In breast tumors, a significantly higher level of Ell3 expression was observed in luminal than in basal tumor types (P < 0.0113)." (PMID 26540344, 2015).
Burkitt lymphoma (1 paper, 2017). A rare form of malignant mature B-cell non-Hodgkin lymphoma. "The effect of ELL3 depletion on cell morphology, latent Epstein Barr Virus (EBV) lytic replication and differentiation markers in a Burkitt's lymphoma (BL) cell line cells are presented." (PMID 29022001, 2017).
ischemic stroke (1 paper, 2015). A stroke disorder caused by obstruction of blood flow to the brain, due to thrombotic (local blood clot formation) or embolic (due to a blood clot or other material traveling from another site) event.
teratoma (1 paper, 2012). A non-seminomatous germ cell tumor characterized by the presence of various tissues which correspond to the different germinal layers (endoderm, mesoderm, and ectoderm). "Teratoma development occurred more rapidly in Ell3-OE cell-injected animals than in controls, while Ell3-KD cell-injected mice did not develop teratomas until 7 weeks following transplantation." (PMID 22768269, 2012).
cancer (5 papers, 2012 to 2019). A tumor composed of atypical neoplastic, often pleomorphic cells that invade other tissues. "RNA polymerase II elongation factor Ell3 is reported to perform distinct functions in embryonic stem cells and cancer cells." (PMID 30654843, 2019). "Ell3 is a RNA polymerase II elongation factor that has various cell type-dependent functions, such as regulating the differentiation efficiency of embryonic stem cells and sensitizing cancer cells to anticancer drugs." (PMID 30654843, 2019). "Indeed, ELL3 has been shown to increase cell proliferation, induce chemoresistance, and increase cancer stem cell populations, potentially through the MEK-extracellular signal-regulated kinase signaling pathway." (PMID 27959953, 2016).
tumor (4 papers, 2015 to 2022). "In summary, the following marker genes were used for subsequent analysis in supratentorial tumours: RELA, ELL3, FBP2, PCP4L1, and MYO3A for detection of RELA+ tumours; and MRAP, IGF1, CAPS, and WWC1 for detection of YAP1+ tumours." (PMID 34314101, 2021).
ELL3 also shares sentences with these, for which no sentence is quoted: B cell lymphoma (1 paper); colorectal cancer (1); head and neck squamous cell carcinoma (1); leukemia (1).